PDCD1 (programmed cell death 1)
Diseases named in the same sentence as PDCD1 in open-access papers (continued):
Sharing a sentence is not in itself a finding about the gene and the disease.
melanoma (continued). "The association between anti-programmed cell death 1 (PD-1) therapy and activation of CD8 T cells specific for mutated antigens in melanoma may warrantstudies with mutated mesothelin-specific responses in patients with GBM undergoing immune checkpoint blockade therapy." (PMID 29113296, 2017). "However, Pdcd-1 is just one example of a melanoma-related gene; little is known about the involvement of other genes, such as perforins, which are DNA methylation-sensitive genes and have been observed to be hypomethylated in autoimmune diseases in our previous studies." (PMID 29100458, 2017). "CXCL13 was found to be preferentially enriched in dysfunctional CD8+ T cells within the melanoma ecosystem, and together with TIGIT, PDCD1 and LAG3, it has been used to define the dysfunctional state of T cells." (PMID 38519500, 2024). "Long-surviving melanoma patients and multiple myeloma patients exhibit reduced CD36 expression on CD8+ T cells and demonstrate responsiveness to programmed cell death 1 (PDCD1, also known as PD-1) treatment." (PMID 38844964, 2024). "Monoclonal antibodies against cytotoxic T-lymphocyte antigen 4 (CTLA-4), programmed cell death 1 (PD-1), and programmed cell death ligand-1 (PD-L1) are approved by the Food and Drug Administration (FDA) for treatment of cSCC, melanoma, and/or MCC." (PMID 38993910, 2023). "In melanoma, FTO promoted resistance to IFN γ-mediated cell death through m6A demethylation of pro-tumorigenic genes Pdcd-1, Cxcr4, and Sox10." (PMID 35350378, 2022). "Demethylation of Pdcd-1, Cxcr4, and Sox10 prevented downstream YTHDF2-mediated mRNA decay, resulting in increased expression of these melanoma-promoting genes." (PMID 35350378, 2022). "In melanoma, FTO promoted cell proliferation and overall tumorigenicity by demethylating m6A on melanoma-promoting genes Pdcd1, Cxcr4, and Sox10." (PMID 35350378, 2022). "FTO knockdown increases m6A modification of PD-1 (PDCD1), CXCR4, and SOX10, contributing to enhanced RNA decay via the m6A reader YTHDF2 in melanoma cells." (PMID 36071523, 2022). "Exploring the clinical significance of PDCD1 and HAVCR2 in melanoma patients, we analyzed the gene expression levels in primary and metastasis melanoma." (PMID 33936081, 2021). "For example in melanoma, FTO expression promotes tumourigenesis and resistance to immunotherapy (anti-PD-1) by directly removing m6A from PDCD1, CXCR4, and SOX10 mRNAs, thereby increasing their stability." (PMID 33461542, 2021). "Further analysis also revealed that Pdcd1 was negatively correlated with AMPK subunit mRNAs including Prkaa1, Prkaa2, and Prkag1 in TCGA database obtained from prostate, melanoma, and breast cancer patients." (PMID 34649584, 2021). "In melanoma, FTO promoted the expression of PDCD1, which expresses the PD-1 protein, as well as CXCR4 and SOX10, promoting melanoma tumorigenesis and resistance to immunotherapy." (PMID 33669361, 2021). "Expectedly, both PDCD1 and HAVCR2 expression were significantly higher in advanced melanoma compared to primary melanoma in the TCGA datasets." (PMID 33936081, 2021). "In conclusion, this study demonstrates the feasibility of PDCD1 editing in effector memory CTL, specific for melanoma antigens and clearly showed their superior efficiency in delaying the growth of PD-L1-positive melanoma tumors." (PMID 32001504, 2020). "We retrieved many known factors for regulating T cell exhaustion among the differentially expressed genes between PDCD1-high and PDCD1-low subsets of the TI CD8+ T cells in human melanoma and NSCLC." (PMID 32111241, 2020). "We analyzed the single-cell transcriptome data derived from human melanoma and non-small cell lung cancer (NSCLC) samples and classified the tumor-infiltrating (TI) CD8+ T cell population based on PDCD1 (PD-1) levels, i.e., PDCD1-high and PDCD1-low cells." (PMID 32111241, 2020).
melanoma (continued). "Monoclonal antibodies targeting the cytotoxic T-lymphocyte-associated antigen 4 (CTLA4) (e.g., ipilimumab [IPI]) and the programmed cell death-1 (PD1) receptor (e.g., nivolumab [NIVO]) represent significant breakthroughs in the treatment of advanced melanoma." (PMID 31312536, 2019). "Immune-related pulmonary toxicity was most frequently observed in trials of lung cancer and of melanoma patients treated with the combination of the anti-cytotoxic T lymphocyte antigen (CTLA)-4 and the anti-programmed cell death-1 (PD-1) antibodies." (PMID 30841554, 2019). "To test this possibility, we identified four representative T/NK modules that tracked with survival differences in distinct tumor types (FOXP3.mod, PDCD1.mod, FLT3LG.mod and KLRB1.mod for bladder, head and neck, kidney and melanoma, respectively)." (PMID 26398410, 2015). "Melanoma, head and neck, and bladder tumors expressing high levels of FLT3LG.mod, PDCD1.mod and FOXP3.mod transcripts, respectively, also expressed significantly higher levels of LCK protein." (PMID 26398410, 2015). "Immunotherapy, such as programmed cell death 1 (PD‐1)/programmed cell death ligand 1 (PD‐L1)/cytotoxic T‐lymphocyte antigen 4 (CTLA‐4) inhibitors, is another parallel approach for the treatment of melanoma." (PMID 41492362, 2026). "Over the past few years, immune checkpoint inhibitors (ICIs) targeting programmed cell death 1 (PD-1), its ligand 1 (PD-L1) and cytotoxic T-lymphocyte antigen-4 (CTLA-4) have radically changed the management of many types of solid tumors including melanoma." (PMID 40554927, 2025). "CD274, PDCD1, CTLA4, and LAG3 were significantly positively correlated with CTHRC1 expression in colon cancer and thyroid cancer; while only CTLA4 was significantly positively correlated with CTHRC1 expression in melanoma." (PMID 39052013, 2024). "Moreover, NK cells with MAP4K1 expression exhibited significantly increased exhaustion signature (PDCD1, TIGIT, HAVCR2, and LAG3) in melanoma tissues (GSE120575 and GSE72056)." (PMID 38828677, 2024). "Moreover, we examined the correlation between CTHRC1 expression and immunotherapy markers, including CD274, PDCD1, CTLA4, and LAG3 in colon cancer, thyroid cancer, and melanoma." (PMID 39052013, 2024). "Notably, Gclc expression in CD8+ T cells was negatively correlated with the exhaustion marker PDCD1 and HAVCR2 in melanoma patients." (PMID 38360744, 2024). "Furthermore, our analysis revealed that within B16F10 melanomas HAVCR2 and LAG3 better characterize the development of a dysfunctional CTL phenotype than does the PDCD1/CD274 axis." (PMID 37182110, 2023). "Considering that CYTL1 may be a potential oncogene in melanoma, it was assessed how CYTL1 interacted with PDCD1, CD274, HAVCR2, TIGIT, SIGLEC15, CTLA4, LAG3, and PDCD1LG2." (PMID 37745303, 2023). "In this study, we take a systems biology approach to compare the importance of cytolytic versus IFNG-mediated cytostatic effects in a murine melanoma model (B16F10) and to dissect the contribution of immune checkpoints HAVCR2, LAG3, and PDCD1/CD274 to CTL exhaustion." (PMID 37182110, 2023). "PDCD1 and CTLA-4 antibodies, which are immune checkpoint inhibitors, have been approved for the treatment of cancers including non-small cell lung cancer (NSCLC) and melanoma, and have improved the prognosis of patients with these cancers." (PMID 36385955, 2022). "In recent decades, immune checkpoint inhibitors (ICIs) and anti-programmed cell death 1 (PD1) antibodies (Abs) have been recognized as anchor drugs for the treatment of advanced melanoma, with or without additional drugs such as anti-CTLA-4 Abs in combination." (PMID 36555362, 2022). "Melanoma, in advanced stages, can metastasize and lead to a lack of immune destruction of abnormal cells by T cells after bypassing the programmed cell death-1 (PD-1) immune checkpoint." (PMID 36569149, 2022). "We further discovered that PDCD1, CTLA4, TIM-3, LAG3, and RTP4 were upregulated in melanomas." (PMID 34154655, 2021).
melanoma (continued). "Interestingly, the checkpoint molecules PDCD1 and HAVCR2 were upregulated in advanced melanoma patients." (PMID 33936081, 2021). "Yang and colleagues found that knocking down only YTHDF2 significantly increased the mRNA stability of PD-1 (PDCD1), CXCR4, and SOX10; in conjunction, the proliferative and migratory capacities of the melanoma cells were increased (in vitro) as was tumor growth (in vivo)." (PMID 34105069, 2021). "We further derived and fully characterized PDCD1-edited T cell clones and demonstrated their superior antitumor activity in comparison with their wild-type counterparts, in NSG mice engrafted with PD-L1 expressing human melanoma tumors." (PMID 32001504, 2020). "Immune checkpoint-based therapies, including extracellular blockade of cytotoxic T lymphocyte antigen 4 (CTLA4) and programmed cell death 1 (PD1/PD-L1), exhibit tremendous clinical success in the treatment of multiple cancer types such as melanoma, leukemia, prostate cancer, and CRC 4,5." (PMID 32226539, 2020). "Although anti-programmed cell death 1 (PD1) antibodies (e.g., nivolumab, pembrolizumab) have been approved as first-line and anchor drugs, respectively, for treating advanced melanoma, the efficacy appears limited as we expected, especially in Asian populations." (PMID 31417907, 2019). "Furthermore, we found that overexpression of PD-1 (PDCD1), CXCR4, or SOX10 inhibited IFNγ-induced cell death in FTO-knockdown melanoma cells." (PMID 31239444, 2019). "Blocking antibody for immune checkpoints such as programmed death-ligand 1 (PD-L1), programmed cell death 1 (PDCD1) and cytotoxtic T-lymphocyte antigen 4 (CTLA4), have been used to treat several tumors including melanoma, renal cell carcinoma, lung cancer and gastric cancer." (PMID 29152078, 2017). "In a chronic LCMV infection model and a melanoma tumor model, anti-PD-L1 therapy did neither downregulate the PDCD1 gene in treated T cells nor did reprogram the epigenetic landscape, including chromatin accessibility to Nr4a and NFAT transcription factors." (PMID 29255458, 2017). "Importantly, LAG3 expression was more abundant than PDCD1 expression in all major TIL subsets in melanoma, unlike in other cancers." (PMID 36719749, 2023). "Nivolumab, an anti–programmed cell death 1 (PD-1) immuno-oncology (I-O) therapy, is approved and regarded as a standard adjuvant treatment option for patients with completely resected stage III or stage IV melanoma based on findings of the pivotal phase III CheckMate 238 trial." (PMID 37835517, 2023). "Immune checkpoint inhibitors (ICIs), such as anti-programmed cell death 1 (PD1) antibodies (Abs) and anti-cytotoxic T-lymphocyte associated protein 4 (CTLA4) Abs, have been widely administered for not only advanced melanoma, but also various non-melanoma skin cancers." (PMID 35409404, 2022). "In single-cell RNA-seq dataset which was originated from melanoma tissue (GSE72056), we downloaded the TPM dataset file and sorted any values more than 3 TPM for cells that highly expressed Foxp3 transcripts and excluded invalid TPM values for Pdcd1 and Prkaa1 expression." (PMID 34649584, 2021). "Importantly, CX3CR1 expression in human melanoma-infiltrating CD8+ T cells was inversely correlated with the expression of PDCD1, TIGIT, and HAVCR2, which is consistent with our previous flow cytometric analyses of mouse melanoma-specific CD8+ T cells and human melanoma CD8+ TILs." (PMID 38881188, 2024). "In particular, following a combination of inhibitors of two checkpoint molecules, programmed cell death 1 (PD1) and CTLA-4, an objective response rate of over 50% was seen in melanoma, although at the cost of significant side effects, most notably autoimmune diseases." (PMID 34959474, 2021).
melanoma (continued). "In contrast to HAVCR2 and LAG3, the dynamics of PDCD1 and CD274 did not coincide with the dynamics of CTL exhaustion, suggesting a relatively minor role for PD-1/PD-L1 as determinants of CTL exhaustion in the B16F10 melanoma model, at least at late stages of anti-tumour immune responses." (PMID 37182110, 2023).
non-small cell lung carcinoma (230 papers, 2016 to 2026). A group of at least three distinct histological types of lung cancer, including non-small cell squamous cell carcinoma, adenocarcinoma, and large cell carcinoma. "Other authors have also linked germline SNPs, such as PDCD1 rs2227981 with a lower risk of treatment-related toxicity of any grade in non-small cell lung cancer patients receiving anti-PD1 nivolumab treatment." (PMID 41153639, 2025). "The -606G allele was associated with higher relative expression of PDCD1 mRNA in peripheral blood mononuclear cells of Japanese and Filipino patients exhibiting subacute sclerosing panencephalitis due to measles infection, and with lower survival in patients with non-small cell lung cancer." (PMID 34290992, 2021). "BACKGROUNDImmune checkpoint inhibitors (ICIs) targeting the programmed cell death 1 axis have revolutionized metastatic non-small cell lung cancer (mNSCLC) treatment." (PMID 41805727, 2026). "Immune checkpoint inhibitors (ICI), such as anti-programmed cell death-1 (PD-1) and anti-programmed cell death ligand-1 (PD-L1) antibodies, have improved the prognosis of patients with non-small cell lung cancer (NSCLC)." (PMID 39853458, 2025). "Programmed cell death 1/programmed death ligand-1 (PD-L1)-based immune checkpoint blockade is an effective treatment approach for non-small-cell lung cancer (NSCLC)." (PMID 39871394, 2025). "Immune checkpoint inhibitors (ICIs), such as programmed cell death-1 (PD-1) inhibitors, have significantly improved survival in various malignancies, including advanced non-small-cell lung cancer." (PMID 41426859, 2025). "In recent years, various types of immunotherapy, particularly the use of immune checkpoint inhibitors targeting programmed cell death 1 or programmed death ligand 1 (PD-L1), have revolutionized the management and prognosis of non-small cell lung cancer." (PMID 38554212, 2024). "Immune checkpoint inhibitors (ICI) therapy based on programmed cell death-1 (PD-1) and programmed cell death ligand 1 (PD-L1) has changed the treatment paradigm of advanced non-small cell lung cancer (NSCLC) and improved the survival expectancy of patients." (PMID 37081866, 2023). "The emergence of immunotherapy, particularly programmed cell death 1 (PD-1) and programmed cell death ligand-1 (PD-L1) produced profound transformations for treating non-small cell lung cancer (NSCLC)." (PMID 37753089, 2023). "Statins were associated with better clinical outcomes in malignant pleural mesothelioma and advanced non-small-cell lung cancer patients treated with programmed cell death-1 (PD-1) inhibitors in a retrospective study." (PMID 35215263, 2022). "In recent years, with the introduction of immune checkpoint inhibitors (ICIs), such as programmed cell death-1 (PD-1) and programmed cell death-ligand 1 (PD-L1) antibodies, the outcomes of metastatic non-small cell lung cancer (NSCLC) have greatly improved." (PMID 36081560, 2022). "Immune checkpoint inhibitors (ICIs) targeting programmed cell death-1 (PD-1) and its ligand programmed cell death ligand-1 (PD-L1) have significantly improved long-term survival in PD-L1 selected patients with advanced non-small cell lung cancer (NSCLC)." (PMID 35902848, 2022). "The Food and Drug Administration (FDA) approved programmed cell death 1 (PD-1) inhibitors such as nivolumab and pembrolizumab for the treatment of stage IV non-small cell lung cancers (NSCLC) in 2014." (PMID 35355539, 2022). "Immune-checkpoint inhibitors (ICI) targeting programmed cell death 1 (PD-1) and its ligand 1 (PD-L1) have quickly changed the treatment landscape in advanced non-small cell lung cancer." (PMID 36189237, 2022). "Immune checkpoint inhibitors (ICIs), targeting programmed cell death-1 (PD-1) and its ligand PD-L1, have significantly prolonged overall survival (OS) of patients with advanced non-small cell lung cancer (NSCLC)." (PMID 33816260, 2021).
non-small cell lung carcinoma (continued). "Nivolumab, a monoclonal antibody targeting programmed cell death-1, significantly prolongs survival for patients with advanced non-small-cell lung cancer (NSCLC)." (PMID 32049805, 2020). "Pembrolizumab is an immune checkpoint inhibitor (programmed cell death 1) approved for use in non-small cell lung carcinoma (NSCLC)." (PMID 32754380, 2020). "Anti–programmed cell death-1 (PD-1)/programmed cell death ligand-1 (PD-L1) immunotherapy is well established for the treatment of non-small cell lung cancer (NSCLC)." (PMID 32303234, 2020). "A 57-year-old Asian man with refractory non-small cell lung cancer under ICIs therapy (pembrolizumab, an anti-programmed cell death-1 monoclonal antibody) developed increased s-Cr levels 5 months after the pembrolizumab initiation." (PMID 32234009, 2020). "The immune checkpoint blockade (ICB) targeting programmed cell death-1 (PD-1) and its ligand (PD-L1) has been proved beneficial for numerous types of cancers, including non-small-cell lung cancer (NSCLC)." (PMID 33243934, 2020). "The combination of programmed cell death-1 (PD-1)/programmed death ligand-1 (PD-L1) inhibitors with chemotherapy has emerged as a promising therapeutic option for advanced non-small-cell lung cancer (NSCLC)." (PMID 32635291, 2020). "Pembrolizumab, an anti-programmed cell death-1 protein monoclonal antibody, is effective for patients with advanced non-small-cell lung cancer." (PMID 30813943, 2019). "Programmed cell death-1 (PD-1) immune checkpoint inhibitor antibody has proven to be effective in advanced non-small cell lung cancer (NSCLC) patients positive for programmed cell death-1 ligand-1 (PD-L1)." (PMID 31174496, 2019). "Immune checkpoint therapies (ICTs) targeting the programmed cell death-1 (PD1)/programmed cell death ligand-1 (PD-L1) pathway have improved outcomes for patients with non-small cell lung cancer (NSCLC), particularly those with high PD-L1 expression." (PMID 31060602, 2019). "Among them, advanced non-small cell lung cancer (NSCLC) has become a major indication for the use of inhibitors of programmed cell death 1 (PD-1) and its ligand (PD-L1)." (PMID 30587227, 2018). "Programmed cell death 1 (PD-1)/PD-1 ligand 1 (PD-L1) checkpoint inhibitors for heavily pre-treated patients with advanced non-small cell lung cancer (NSCLC) represent major advances in immunotherapy." (PMID 29228707, 2017). "Nivolumab is a fully human IgG4 programmed cell death 1 immune checkpoint inhibitor monoclonal antibody approved for the treatment of non-small cell lung cancer (NSCLC)." (PMID 28861280, 2016). "Herein, we report the case of a 68-year-old male with non-small cell lung cancer(NSCLC) who received two cycles of programmed cell death-1 (PD-1) antibody sintilimab immunotherapy combined with albumin-bound paclitaxel and carboplatin chemotherapy and one cycle of sintilimab monotherapy." (PMID 38957321, 2024). "Immune checkpoint inhibitors targeting the programmed cell death-1 (PD-1) protein significantly improve survival in patients with advanced non-small-cell lung cancer (NSCLC), but its impact on early-stage ground-glass opacity (GGO) lesions remains unclear." (PMID 38637495, 2024). "The CD274 and PDCD1 immune checkpoint interaction could accelerate cancer progression in the colorectal cancer microenvironment and elderly non-small cell lung cancer patients." (PMID 37608927, 2023). "This study aimed to investigate whether continuous assessment of LIPI has predictive value for chemoimmunotherapy in non-small cell lung cancer (NSCLC) patients receiving first-line programmed cell death 1 (PD-1) inhibitor plus chemotherapy." (PMID 37304273, 2023). "In addition, the development of programmed cell death 1 (PD-1)/PD-1 ligand 1 (PD-L1) checkpoint inhibitors has changed the pattern of non-small cell lung cancer treatment and achieved certain therapeutic effects." (PMID 33552086, 2020).